CDKN2A (cyclin dependent kinase inhibitor 2A)
Diseases named in the same sentence as CDKN2A in open-access papers (continued):
Sharing a sentence is not in itself a finding about the gene and the disease.
Hyperglycemia (11 papers, 2011 to 2024). An increased concentration of glucose in the blood. "Data indicated that decreased DNA methylation levelsat CpG sites in the CDKN2A and CDKN2B gene promoterin pancreatic islets of the rat offspring were associatedwith maternal hyperglycemia." (PMID 31721535, 2020). "This gives rise to thespeculation that maternal hyperglycemia may change thenormal DNA methylation pattern of cell cycle inhibitorygenes CDKN2A and CDKN2B in pancreatic islets of ratoffspring." (PMID 31721535, 2020).
Hypertension (11 papers, 2012 to 2024). The presence of chronic increased pressure in the systemic arterial system. "ADTRP (rs6903956), CDKN2A/B (rs10757274) and clinical characteristics (T2DM, hypertension and hyperlipidemia) were included in the gene-environment interactions analysis, adjusting for age, gender, ethnicity, BMI, and smoking and drinking habits as covariates." (PMID 25430018, 2014).
liver fibrosis (11 papers, 2013 to 2025). "Furthermore, we examined the relative mRNA expression levels of key markers related to hepatic fibrosis (Acta2, Cola2, TGF-β1, and MMP2), cirrhosis (CXCR4, SOX9, DCN, and MFAP4), and cancer (Bcl2, CDKN2a, c-Myc, and Fn1) across the experimental groups." (PMID 39851554, 2025). "In contrast, aged mice exhibited hepatic fibrosis, with increased collagen deposition and upregulation of genes related to fibrosis (Acta2, MMP2, TGF-ß1, and Col1a2), cirrhosis (CXCR4, SOX9, DCN, and MFAP4), and cancer (Bcl2, CDKN2a, c-Myc, and Fn1)." (PMID 39851554, 2025).
malignant pleural mesothelioma (11 papers, 2017 to 2024). A malignant neoplasm that arises from mesothelial cells in the pleura and shows a diffuse growth pattern. "Malignant pleural mesotheliomas are mostly characterized by frequent deletions (50–80%) of the CDKN2A/B locus (encoding the CDK4/6 inhibitors p16INK4A and p15INK4B), which are associated with shorter overall survival." (PMID 36453028, 2024). "Proportion of CDKN2A homozygous loss according to malignant pleural mesothelioma (MPM) subtype." (PMID 33304846, 2020). "Comparison of fluorescence in situ hybridization (FISH) results for detecting methylthioadenosine phosphorylase (MTAP) and CDKN2A deletion in malignant pleural mesothelioma (MPM) cases." (PMID 33304846, 2020). "Comparison of droplet digital PCR (ddPCR) results for detecting methylthioadenosine phosphorylase (MTAP) and CDKN2A deletion in malignant pleural mesothelioma (MPM) cases." (PMID 33304846, 2020). "Loss of expression of BRCA1 associated protein (BAP1) or methylthioadenosine phosphorylase (MTAP) or homozygous deletion of cyclin‐dependent kinase inhibitor 2A (CDKN2A) (p16) by FISH helps to distinguish reactive mesothelial cells from malignant pleural mesothelioma." (PMID 36069384, 2022). "The CDKN2A gene plays a central role in the pathogenesis of malignant pleural mesothelioma (MPM)." (PMID 33828993, 2021). "Homozygous, hemizygous and no loss of CDKN2A detected by fluorescence in situ hybridization (FISH) in malignant pleural mesothelioma (MPM) cases." (PMID 33304846, 2020). "Homozygous, hemizygous and no loss of CDKN2A detected by droplet digital PCR (ddPCR) in malignant pleural mesothelioma (MPM) samples." (PMID 33304846, 2020). "CDKN2A is frequently co-deleted with MTAP, while the status of MTAP IHC expression reflected the status of CDKN2A in malignant pleural mesothelioma diagnosis." (PMID 31965001, 2020).
oesophageal cancer (11 papers, 2010 to 2024). "In primary esophageal carcinomas and cell lines, deletions and point mutations in CDKN2A gene have been reported in 16% to 82% of cases, and hypermethylation of promoter region in 20% to 88% of ESCC and precancerous lesions." (PMID 20163722, 2010). "In a previous paper, hypermethylation of CDKN2A exon 2 has been associated with oesophageal cancer." (PMID 28403857, 2017). "Hypermethylation of CDKN2A exon 2 has previously been linked to late stage oesophageal cancer." (PMID 28403857, 2017). "Among these CRGs, CDKN2A is outstanding for it has high expression in almost all cancer except for esophageal carcinoma (ESCA), while the remaining nine genes have distinct expression patterns in specific cancer types." (PMID 36845390, 2023). "Further investigations will show if hypermethylation of CDKN2A exon 2 is limited to breast and oesophageal cancer, or also occurs in other types of cancer." (PMID 28403857, 2017).
osteoarthritis (11 papers, 2014 to 2025). A noninflammatory degenerative joint disease occurring chiefly in older persons, characterized by degeneration of the articular cartilage, hypertrophy of bone at the margins and changes in the synovial membrane. "Additionally, five genes related to cuproptosis (FDX1, LIPT1, PDHA1, PDHB, and CDKN2A) are considered candidate biomarkers or therapeutic targets for osteoarthritis synovitis." (PMID 39360273, 2024). "To determine whether cellular senescence plays a role in osteoarthritis development, we generated conditional Tnfrsf11aCre/+; Cdkn2aflox/flox mice, in which the senescence gene Cdkn2a is deleted in RANK+ osteoclast lineage cells." (PMID 35881544, 2022). "Therefore, deletion of Cdkn2a in osteoclast lineage cells attenuated HFD-induced osteoarthritis progression." (PMID 35881544, 2022).
ovarian tumor (11 papers, 1996 to 2024). "CDKN2A (p16INK4a), which is known to inhibit CDK4 and CDK6, was deleted or downregulated in 21% of the ovarian tumours." (PMID 38612869, 2024).
Peutz-Jeghers syndrome (11 papers, 2014 to 2025). An autosomal dominant disorder caused by pathogenic variants in the STK11 gene, characterized by hamartomatous polyps in the gastrointestinal tract, mucocutaneous pigmentation and increased risk of GI and extra-GI malignancies. "Age of starting screening varies among risk factors: Individuals with Peutz Jeghers syndrome or CDKN2A mutations are recommended to start screening at age of 40." (PMID 35326524, 2022). "In conclusion, the diagnostic yield of PDAC was substantial in high-risk mutation carriers, in particular in CDKN2A mutation carriers and patients with Peutz-Jeghers syndrome, but non-existent in the mutation-negative FPC kindreds." (PMID 33820756, 2022).
T-cell lymphoma (11 papers, 2008 to 2023). "To confirm this finding and to compare TYMS levels among different non-Hodgkin lymphoma transcriptomes, we used a different dataset that showed B and T cell lymphomas (n = 32) express high TYMS levels that correlated with low levels of CDKN2A expression." (PMID 37106126, 2023). "Deletions in CDKN2A/B are also common in canine histiocytic sarcoma, 62.8%, T-cell lymphoma, 55.6%, and canine fibrosarcoma, 100%." (PMID 33556121, 2021). "Various tumour suppressor genes have been shown to be frequently hypermethylated in NK/T-cell lymphoma including p73, CDKN2A, CDKN2B, hMLH1 and RARβ, but hypermethylation of miR-124-1 is one of the first reports of methylation of miR in NK/T-cell lymphoma." (PMID 21544199, 2011). "Despite barely detectable in normal thymic CD3+ T cells, ZBTB7A is highly expressed in a subset of human T-cell lymphoma, and its overexpression induces the development of a mouse precursor T-cell lymphoma by directly repressing the transcription of the tumor suppressor gene Cdkn2a (Arf)." (PMID 34349770, 2021).
Barrett esophagus (10 papers, 2007 to 2025). Esophageal lesion lined with columnar metaplastic epithelium which is flat or villiform.
gliosarcoma (10 papers, 2016 to 2023). A rare histological variant of glioblastoma (WHO grade IV) characterized by a biphasic tissue pattern with alternating areas displaying glial and mesenchymal differentiation (WHO). "Given its significance as a poor prognostic marker in GBM, further investigation into the implications of CDKN2A loss in gliosarcoma is warranted." (PMID 34504233, 2021). "We found CDKN2A had an alteration frequency of 31% among the gliosarcoma samples, specifically representing copy number losses and an inactivating mutation." (PMID 34504233, 2021). "Gliosarcoma mutations with potential therapeutic indications include BRAF, EGFR, CDKN2A, NF1, and PTEN." (PMID 34504233, 2021). "Homozygous loss of CDKN2A is common in GBM (35–50%) and loss of this locus occurred in 14 of 18 gliosarcoma specimens." (PMID 31073965, 2019). "Pathways associated with copy number loss in the gliosarcoma cohort included WNT signaling, NF-kß, and CDKN2A." (PMID 31073965, 2019). "In case 2, Oncomine Comprehensive v3 analysis of the local left frontal gliosarcoma recurrence detected an EML4:NTRK3 fusion, a CDKN2A/B loss and an MRE11A alteration of unknown significance." (PMID 33353026, 2020). "Among the most frequently altered genes found in gliosarcoma, BRAF, EGFR, PTEN, NF1, and CDKN2A are potentially targetable according to OncoKB." (PMID 34504233, 2021). "Of the 19 common genes in gliosarcoma, five (BRAF, EGFR, CDKN2A, NF1, and PTEN) were indicated as potentially targetable genes present in the OncoKB database." (PMID 34504233, 2021). "Based on the detected CDKN2A/B deletion, we further tested the potential of the CDK4/6 inhibitor abemaciclib, which showed strong efficacy against both gliosarcoma cell models and entrectinib distinctly synergized with 5 μM abemaciclib in vitro." (PMID 33353026, 2020).
Insulin resistance (10 papers, 2016 to 2024). Increased resistance towards insulin, that is, diminished effectiveness of insulin in reducing blood glucose levels. "Apart from causing insulin resistance, evidence showed that Cdkn2a (or more specifically p16INK4a) also protected against age-related pancreatic function decline." (PMID 35055468, 2022). "The findings suggest that mutations at the CDKN2A locus may limit skeletal muscle PGC-1α induction and contribute to insulin resistance, diminished physical fitness, and increased adiposity." (PMID 37395281, 2023). "This reveals a protective role of INK4A/ARF locus against age-induced insulin resistance, whereas increased insulin secretion, attenuated insulin sensitivity, and reduced hepatic insulin clearance were observed upon loss of function mutation of the Cdkn2a gene." (PMID 36143369, 2022). "Additionally, abnormal expression of CDKN2A in adipose tissue may lead to insulin resistance." (PMID 38904034, 2024).
kidney cancer (10 papers, 2013 to 2025). Primary or metastatic malignant neoplasm involving the kidney. "In 2006 we determined the frequency of the CDKN2A p.A148T polymorphism in 223 patients with urothelial bladder cancer and 245 patients with kidney cancer." (PMID 35478773, 2022). "Of the kidney cancer patients enrolled in the study, fourteen (3.4%) carried a CDKN2A p.A148T polymorphism (OR = 0.9; 95% CI 0.55–1.70; p = 0.9)." (PMID 35478773, 2022). "In particular, recent studies support a genetic predisposition of coexisting MM and kidney cancer in the same patient, such as microphthalmia-associated transcription factor, CDKN2A and B-RAF." (PMID 23653675, 2013). "Seven patients with kidney cancer who carried the CDKN2A variant had died by February 2021." (PMID 35478773, 2022). "Thus, the NOD2 c.3020insC or the CDKN2A p.A148T polymorphism cannot be added to the list of genes that are associated with an increased susceptibility to bladder or kidney cancer at this time." (PMID 35478773, 2022). "A decrease in cell proliferation and an increase in apoptosis through promoter demethylation and the upregulation of CDKN2a was also observed by genistein (25–100 μM) in kidney cancer cell lines." (PMID 32878338, 2020). "For kidney cancer, a maximum sensitivity and specificity of 88% and 100%, respectively, were found for VHL, p16/CDKN2a, p14ARF, APC, RASSF1A, and Timp-3." (PMID 40141826, 2025).
medulloblastoma (10 papers, 2007 to 2026). A malignant, invasive embryonal neoplasm arising from the cerebellum. "CDKN2A suppressed RB phosphorylation less effectively in tumor cells than in CGNPs, as the pRB+ fractions of CDKN2A+ cells were significantly higher in M-Smo/EedcKO and M-Smo/Ezh2cKO medulloblastomas compared to P7 EedcKO cerebella." (PMID 36635771, 2023). "Homozygous deletions of (i) the 9p21.1–p21.3 region encompassing CDKN2A, CDKN2B and ARF and (ii) the 6q23.1 region, each observed in a single cell line, have previously been reported in medulloblastoma and other cancer types." (PMID 19584924, 2009). "In SHH medulloblastomas, disrupting PRC2 activity through deletion of either Eed or Ezh2 was sufficient to allow widespread expression of genes typically suppressed by the PRC2, including the CDKN2A tumor suppressor." (PMID 36635771, 2023). "CDKN2A was thus up-regulated in both Eed-deleted and Ezh2-deleted medulloblastomas but did not restrict RB phosphorylation or tumor progression." (PMID 36635771, 2023).
pancreatic neuroendocrine tumor (10 papers, 2016 to 2025). Pancreatic endocrine tumor, also known as pancreatic neuroendocrine tumor (PNET), describes a group of endocrine tumors originating in the pancreas that are usually indolent and benign, but may have the potential to be malignant. "Furthermore, MUTYH/CHEK2, BRCA2, CDKN2A, and TIMP3 have also been associated with pancreatic neuroendocrine tumors." (PMID 35163032, 2022). "Pancreatic NETs frequently exhibit changes in genes such as MEN1, DAXX, ATRX, TSC1, TSC2, CDKN1A, and CDKN1B, along with alterations in CDKN2A and SETD2 in metastatic lesions." (PMID 41426335, 2025).
papillary thyroid carcinoma (10 papers, 2006 to 2025). "CDKN2A’s deletion has been previously reported to be associated with poor survival in anaplastic thyroid cancer or advanced differentiated thyroid cancers patients and poorest thyroid differentiation, which is consistent with our results." (PMID 36060256, 2022). "The recurrence risk of papillary thyroid carcinoma can be preoperatively predicted using miRNA-221, FN1, and CDKN2A genes." (PMID 39000197, 2024). "In Hu’s study, three genes (ITPR1, CCL2, and CDKN2A) were selected to predict papillary thyroid carcinoma patients’ survival." (PMID 35580861, 2022). "The loss of CDKN2A copy number and the absence of p16INK4A were significantly associated with reduced disease-specific survival in patients with ATC and advanced differentiated thyroid cancers." (PMID 40363930, 2025).
peritoneal mesothelioma (10 papers, 2012 to 2025). A benign or malignant mesothelial neoplasm that arises from the peritoneum. "MTAP immunohistochemistry (IHC) was evaluated as a diagnostic tool for peritoneal mesothelioma by comparing it with CDKN2A homozygous deletion (HD) detected by FISH." (PMID 40566743, 2025). "Aside from its diagnostic value, the presence of a higher rate of CDKN2A HD has also been demonstrated to significantly worsen the prognosis in both pleural and peritoneal mesotheliomas." (PMID 40566743, 2025). "The frequent deletion of the Cdkn2a/2b locus is observed in the rat peritoneal mesothelioma, an iron overload-associated tumor, induced either by another iron compound (ferric saccharate) or by asbestos." (PMID 22952676, 2012). "Our study represents the first formal evaluation of the reliability of MTAP IHC as a surrogate of CDKN2A FISH in a cohort of only peritoneal mesothelioma." (PMID 40566743, 2025). "The aim of our study was to evaluate the reliability of MTAP IHC as a surrogate marker for CDKN2A HD in peritoneal mesothelioma." (PMID 40566743, 2025). "Furthermore, in the peritoneal mesothelioma cohort in the previously cited study, the most common alterations detected in peritoneal mesothelioma were inactivating mutations in BAP1 (47.9%), NF2 (26.5%), CDKN2A (25.9%), CDKN2B (19.5%) and PBRM1 (15.8%)." (PMID 38136262, 2023). "We detected CDKN2A deletions in 48.2% of pleural and in 25.9% of peritoneal mesothelioma." (PMID 36138075, 2022). "Data presented in this report provide further evidence for the role of tumor suppressor genes such as CDKN2A, NF2 in the pathogenesis of peritoneal mesothelioma, and presents several other mutations that may also play key roles in the natural history of this disease." (PMID 25798586, 2015). "The receiver operating characteristic (ROC) curve confirmed the results obtained in the first concordance analyses with Cohen's Kappa, proving that MTAP IHC is not informative for the status of CDKN2A copy number in our peritoneal mesothelioma cases." (PMID 40566743, 2025). "Similarly, a combination of CDKN2A homozygous deletion and NF2 hemizygous loss is a negative prognostic factor for patients with peritoneal mesothelioma." (PMID 37180489, 2023). "Likewise, a combination of homozygous CDKN2A deletions and hemizygous NF2 loss in peritoneal mesotheliomas has been shown to be an independent negative prognostic factor for both PFS and OS." (PMID 29565815, 2018). "Results showed low concordance between MTAP IHC and CDKN2A HD, suggesting MTAP IHC is not reliable for predicting CDKN2A HD in peritoneal mesothelioma." (PMID 40566743, 2025). "Third, given the similar genomic landscape of both pleural and peritoneal mesothelioma (copy number-driven somatic alterations including high BAP1 and CDKN2A inactivation frequency), there was no expectation of widely differing responses to anti-PD-1 checkpoint inhibition between these subtypes." (PMID 34656227, 2021).
anaplastic thyroid cancer (9 papers, 2021 to 2025). "CDKN2A loss has been reported in anaplastic thyroid cancer, but the frequency of this genetic alteration in RET-rearranged cancer is unknown." (PMID 35510953, 2022). "Additionally, a transcriptome analysis revealed that CDKN2A deletions in ATC correlated with lower thyroid differentiation scores, suggesting that CDKN2A status may be a prognostic marker for advanced differentiated and anaplastic thyroid cancer." (PMID 40363930, 2025).
bladder urothelial carcinoma (9 papers, 1999 to 2025). "The most frequent genetic alteration in transitional cell carcinoma of the urinary bladder (TCC) is loss of chromosome 9 which targets CDKN2A on 9p." (PMID 11747331, 2001). "For example, in colon adenocarcinoma (COAD), bladder urothelial carcinoma (BLCA), and liver hepatocellular carcinoma (LIHC), the high expression of CDKN2A is correlated with poor prognosis in patients." (PMID 40861807, 2025). "Previous studies showed that neither CDKN2A gene nor CDKN2A (p16) protein expression was an independent predictor, but the combination of gene and protein status was an important predictor of urothelial bladder carcinoma." (PMID 33896386, 2021).